MYOD1 (myogenic differentiation 1)
Diseases named in the same sentence as MYOD1 in open-access papers (continued):
Sharing a sentence is not in itself a finding about the gene and the disease.
tumor (continued). "Immunohistochemical staining demonstrated positive expression of Desmin, Myogenic Differentiation 1 (MyoD1), and Myogenin in the tumor cells, with a Ki-67 proliferation index of 70%, while were negative for CD20, cytokeratin (CK), CD79a, CD38, and chromogranin A (CgA)." (PMID 40520793, 2025). "These tumor cells were positive for Desmin, MyoD1, and Myogenin." (PMID 40040389, 2025). "The tumor cells were variably positive for desmin, myogenin, and MYOD1." (PMID 39439633, 2024). "Additionally, the tumor was positive for desmin, myogenin, and MYOD1, suggesting skeletal muscle differentiation." (PMID 39439633, 2024). "The tumor cells were positive for immunohistochemistry markers desmin, MyoD1, and vimentin." (PMID 38500901, 2024). "Immunohistochemically, tumor cells were positive for MyoD1 and desmin." (PMID 37621777, 2023). "To test our hypothesis that our primary cell line was of myogenic lineage, we stained the tumor and clonal cells with MyoD1." (PMID 37349371, 2023). "This is in line with the notion that FN tumours often exhibit an undifferentiated “embryonal” histology, while FP more widely express the key myogenic regulatory factors responsible for orchestrating terminal differentiation, MYOD1 and MYOG6." (PMID 37244912, 2023). "Patients aged <1 year with VGLL2, SBF, TEAD1, and NCOA2 gene fusions had a better prognosis, whereas patients with a MYOD1 gene mutation demonstrated stronger tumor aggression and higher mortality, regardless of age." (PMID 36686750, 2022). "Experimental evidence suggests that the effectiveness of low-dose decitabine in malignancies stems from its ability to demethylate silenced tumor-suppressor genes related to leukemic malignancies and other myeloid disorders such as p15INK4b, E-cadherin and MYOD1." (PMID 34358067, 2021). "Depending on the activating/repressive function of individual transcription factors, IDR-mutated proteins can be both oncogenes (with MYOD1 mutations promoting the dimerization with MYC), or tumor suppressors (with ID3 mutations impairing its repressor activity)." (PMID 33806614, 2021). "Notably, the expression of WT1 and cyclin D1 was also retained in those cases in which the conventional tumor markers (myogenin, desmin and MyoD1 for RMS; CD99 for EWS; NB84 for NB) were focally expressed or more rarely absent." (PMID 34943491, 2021). "In immunohistochemistry, tumor cells partly express cytoplasmic MyoD1." (PMID 32000418, 2020). "Both the distribution and the size of tumor were remarkably reduced by MyoD1 overexpression." (PMID 31831855, 2020). "Immunohistochemically, the tumor cells are positive for desmin, myogenin, and MYOD1." (PMID 32867125, 2020). "The dynamic expression of MYOD1/NOG markers suggests that these cells may behave as early progenitors able to sustain tumor growth." (PMID 32300280, 2020). "Combined with the data obtained from miRNA-overexpressing and virus-infected cells, we finally identified the host RBM24 and MYOD1 genes as two biological targets for miR-M2-5p, which have been frequently reported as important tumor suppressors in previous studies." (PMID 33224130, 2020). "In pleomorphic RMS, the tumor cells are positive for desmin, myogenin, and MYOD1." (PMID 32867125, 2020). "Such a role would not preclude the possibility that MYOD1+ tumor cells drive recurrence, as MYOD1-expressing cells may have mechanisms that overcome a putative tumor-suppressive effect." (PMID 31863004, 2019). "In our patient, the tumor was positive for desmin, myogenin, and MyoD1." (PMID 29804543, 2018). "By immunohistochemistry, tumor cells in 21 of 21 cases were positive for desmin; in 18 of 20 were positive for MYOD1 in a diffuse pattern; in 17 of 19 were positive for myogenin; and in 6 of 11 cases were positive for smooth muscle actin, mostly in a focal pattern." (PMID 27562493, 2016).
tumor (continued). "However, since our tumors developed orthotopically in host skeletal muscle, care was exercised to ensure that reactive/atrophic MyoD1+ entrapped skeletal muscle cells were distinguished from MyoD1+ tumor cells." (PMID 25992772, 2015). "The tumor cells were strongly positive for Vimentin, Desmin and MyoD1." (PMID 23379991, 2013). "In addition, MYOD1 directly regulates SKP2 (S-phase kinase associated protein-2) in RMS, a substrate recognition subunit of the E3 ubiquitin ligase complex that is necessary for tumor cells to maintain cell cycle progression." (PMID 39902277, 2024). "Subsequently, the tumor was tested for MYOD1 (L122R) mutation and was found to be negative." (PMID 35642345, 2023). "Histologically, the ASPcKOP7cKO tumor cells stained sporadically for DESMIN but were no longer positive for RMS diagnostic markers MYOD1 and MYOGENIN; this was specific for ASPcKOP7cKO tumors as ASPcHetP7cKO and ASPcKOP7cHet tumors were still myogenic, small round blue tumors consistent with RMS." (PMID 34535684, 2021). "Other protective genes, including DYRK1A, DICER1, MYOD1 and INTS6, also contribute to tumor suppression through diverse mechanisms." (PMID 40561176, 2025). "The results revealed the presence of desmin (DES) in the majority of tumor cells and the focal expression of myogenin (MYOG) and MYOD1." (PMID 41373578, 2025). "In both tumor-free and tumor-bearing mice treated with WFA, we observed a significant increase in Pax7 levels and a notable rise in Myod1 expression compared to the vehicle-treated groups." (PMID 39996717, 2025). "Although MYOG is transcriptionally regulated by MYOD1 and expressed in RMS, the ability of MYOG+ cells to proliferate and reproduce the full FN-RMS tumor is debated." (PMID 39902277, 2024). "Following KD of MYOD1 in FN-RMS, cells exhibited decreased proliferation, cell-cycle arrest, decreased tumor sphere formation, and increased cell death." (PMID 39902277, 2024). "All detectable tumor lesions expressed CD56 (+++, membranous), MYOD1 (+++, nuclear), DESMIN (+, cytoplasmic) and MYOGENIN (++, nuclear)." (PMID 37662907, 2023). "In addition, the tumor was tested for MYOD1 (L122R) mutation by polymerase chain reaction (PCR), using forward and backward primers, followed by Sanger sequencing and was proved to be negative for MYOD1 (L122R) mutation." (PMID 35642345, 2023). "The biopsy results revealed a mesenchymal malignant tumor, tumor cell cytoplasm transparent or red staining, some showed acinar arrangement, tumor cell immunophenotype: CK (−), Vim (+), CD34 (+), MyoD1 (plasma +), SMA (focal +), CD56 (−), CgA (−)." (PMID 36467475, 2022). "The tumor-free and tumor-bearing WFA-treated groups displayed significant increases in Pax7 compared to the tumor-free vehicle-treated group and a significant increase in Myod1 compared to both vehicle-treated groups." (PMID 33718372, 2021). "To examine the role of MyoD1 in GC progression in vivo, we inoculated LV-MyoD1-MKN-45 and control cells into nude mice, respectively, and examined tumor distribution and size on the 21st day after injection." (PMID 31831855, 2020). "Here, we report the identification of two tumor suppressors, the RNA-binding protein 24 (RBM24) and myogenic differentiation 1 (MYOD1), being two biological targets for miR-M2-5p." (PMID 33224130, 2020). "Histologically, the tumours stained negatively for CD31, DESMIN, MYOD1, MYOGENIN, alpha-SMA and positively for VIMENTIN." (PMID 28982163, 2017). "Immunohistochemical analysis revealed the following results: Tumor cells were negative for Ckp, positive for desmin and actin, negative for myogenin, positive for MyoD1, and negative for CgA, S-100, Syn, h-caldesmon, SMA, Sox-10, Pax-8, and GATA3." (PMID 39139286, 2024).
tumor (continued). "Because of the interconnected nature of myogenic TFs and the genes they regulate, targeting a specific core regulatory TF, like MYOD1, or PAX3/7-FOXO1 is likely to collapse the tumor transcriptome resulting in terminal differentiation of tumor cells or tumor cell death." (PMID 39902277, 2024). "Cytologic analysis demonstrated diffuse sheets of round tumor cells with variable amounts of cohesive eosinophilic cytoplasm and rhabdomyoblasts, and immunohistochemical (IHC) staining for DESMIN, MYOD1, and MYOGENIN consistent with the human solid subtype of ARMS." (PMID 37968277, 2023). "The tumor cells did not express pan-cytokeratin, desmin, MyoD1, Myogenin, Melan-A, HMB45, EMA, S-100, SOX-10, IgG4, and pan-TRK." (PMID 37735390, 2023). "Immunohistochemically, the tumor cells were positive for desmin, MYOD1 and SMA, focally positive for myogenin, while negative for h-caldesmon, SOX10 and S100P." (PMID 35642345, 2023). "Immunohistochemically, tumor cells demonstrated membranous positivity for CD99, positivity for Nkx2.2, focal positivity for S100 and negativity for desmin, myogenin, MyoD1, cytokeratin (AE1/AE3), CD31, CD34, CD3, CD20, and CD1a." (PMID 34749732, 2021). "Interestingly, PAX7 along with MYOD1 are the only genes that are both members of FN-RMS core-regulatory circuits and are FN-RMS dependencies thus coupling tumor cell identity and survival 34,35." (PMID 34535684, 2021). "RT-PCR confirmed SRF-NCOA2 fusion both in the tumor evaluated at diagnosis (T) and in the S-RMS1 cell line at different passages (passage 3 above panel, passage 7 below panel) as well as positivity for MyoD-1 and myogenin." (PMID 34067464, 2021). "The staining of RMS tumor cells with Myogenin and MyoD1 revealed that B7-H3 is expressed by tumor cells and not detected in the stroma or tumor-infiltrating immune cells." (PMID 34572755, 2021). "In contrast, the transcription of myogenesis‐related gene Myod1 was lower in GA muscle of YES2‐bearing mice than that in non‐tumour‐bearing mice (P = 0.02, P = 0.001, P = 0.0067, respectively)." (PMID 33732415, 2021). "By immunohistochemistry, the tumor cells stained positively for S-100 (focal +), CD34 (strong +++) and Ki-67 (20%), and negatively for smooth muscle actin, pan-cytokeratin, neurofilament, pan-cytokeratin-L, GFAP, CD31, STAT6, ERG, myogenin, and MyoD1." (PMID 32590748, 2020). "Immunohistochemically, the tumor cells were positive for transcription factor E3 (TFE3) (which confirmed the histological diagnosis of ASPS), myogenic determination factor 1 (MyoD1), and (focal) PAS-D, with negativity for desmin and synaptophysin." (PMID 32000418, 2020). "Desmin and MYOD1 positivity of most cells, irrespective of their morphology, indicated the myogenic origin of the tumor." (PMID 33322555, 2020). "Human MYOD1 gene is located at 11p15, a chromosomal region containing the IGF2 and H19 imprinted genes, whose expression has been found to be altered (over-expression of IGF2 and downregulation of H19) in a subset of ERMS tumours." (PMID 27764816, 2016). "In a remaining single case, wherein MYOD1 was negative and myogenin was not performed, tumor cells were positive for myoglobin." (PMID 27562493, 2016). "The tumor cells are negative for S100 (positive in melanoma), myogenin, MyoD1 (positive in spindle cell tumors of skeletal muscle differentiation), and SMA (positive in spindle cells tumor of smooth muscle differentiation)." (PMID 25960902, 2015). "The pleomorphic tumor cells were strongly positive for desmin and focally positive for myoD1 but negative for myogen (Myf-4), CD117, CD34, and DOG1 IHC, suggesting rhabdomyosarcomatous differentiation." (PMID 25694839, 2015). "The cell derives its name from the resemblance to rhabdomyoblasts, although current evidence does not support a myogenic origin as these tumours lack immunoreactivity for muscle differentiation with MyoD1 and myogenin." (PMID 25243090, 2014).
tumor (continued). "Immunostaining showed that the tumor was strongly positive for Vimentin, Desmin and MyoD1, and was negative for CK, P63, NSE, CD45, CD30, S-100, CD99, Myoglobin, CD68, CD34, CD31, α–SMA." (PMID 23379991, 2013). "Immunostaining showed that the tumor was positive for the Vimentin, Desmin and MyoD1, and was negative for CK, P63, NSE, CD45, CD30, S-100, CD99, Myoglobin, CD68, CD34, CD31, and α–SMA." (PMID 23379991, 2013). "The prediction of mesenchymal transcription factor activity (MYOD1 and YY1) could be indicative of an epithelial-mesenchymal transition, which has lately been related to tumor progenitor cell plasticity." (PMID 20500816, 2010). "Immunohistochemically the tumor cells strongly expressed Vimentin, MyoD1, SMA and CD99, being negative for the remaining antibodies tested, including Myogenin and Desmin." (PMID 20701800, 2010). "In the IHC study, tumor cells showed positivity for CD99, EMA, vimentin, and TLE1, while they were negative for NKX2.2, WT1, BCOR, PDGFA, cytokeratins, muscle markers (smooth muscle actin, desmin, caldesmon, MyoD1, and myogenin), and melanocytic markers (HMB45, SOX10, and S100)." (PMID 38339014, 2024). "The importance of identifying this rare tumor is in view of its relatively favorable prognosis, unlike a spindle cell/sclerosing RMS that invariably shows an aggressive clinical course, in adult patients, especially those displaying the MYOD1 (L122R) mutation." (PMID 35642345, 2023). "By immunohistochemistry, the tumor cells stained positively for S-100 (focal +), CD34 (strong +++), and Ki-67 (20%), and negatively for smooth muscle actin, pan-cytokeratin (CK), neurofilament (NF), pan-cytokeratin-L, GFAP, CD31, STAT6, ERG, myogenin, and MyoD1." (PMID 32590748, 2020). "None of the tumours exhibited nuclear staining for the skeletal muscle markers MYOD1 and MYOGENIN." (PMID 29731980, 2018). "Tumor cells were negative for muscle-specific actin, epithelial membrane antigen, smooth muscle actin, cytokeratin pan, S100, desmin, glial fibrillary acidic protein, myogenin, MyoD1 and F8." (PMID 24758544, 2014). "Indeed, while these tumours showed high levels of H-RAS expression in comparison to adjacent normal tissue and were immunoreactive for the common mesenchymal marker VIMENTIN, the tumour cells did not stain for lineage markers including CD31, vWF, DESMIN, SMA, MYOD1 or MYOGENIN (last column)." (PMID 29731980, 2018). "Immunohistochemical examination showed that tumor cells were strongly positive for vimentin, SMA, and P16 but negative for desmin, CK, P40, P63, CK5, HMB45, MyoD1, myogenin, S100, and SOX10." (PMID 39872225, 2025). "Immunohistochemically, vimentin, SMA, and P16 were diffuse positive in tumor cells, whereas desmin, CK, P40, P63, CK5, HMB45, MyoD1, myogenin, S100, and SOX10 were all negative." (PMID 39872225, 2025). "Immunohistochemically, vimentin, smooth muscle actin (SMA), and P16 were diffuse positive in tumor cells, whereas desmin, cytokeratin (CK), P40, P63, CK5, HMB45, MyoD1, myogenin, S100, and SOX10 were all negative." (PMID 39872225, 2025). "However, IF staining of tumor sections revealed that the tumor cells did not express MyoD1 and myogenin, markers of RMS cells, suggesting that this inconsistency between clinical SHP2 GOF mutation in patients and mouse sarcomagenesis could be associated with the origin and species of MSCs." (PMID 38451719, 2024). "The tumor cells were negative expression of CgA, CD56, CK5/6, CK20, Myogenin, MyoD1, Desmin, CEA, S100, CK8/18, CDX2, CD20, CD5, CD3, CD79a, LCA and HMB45." (PMID 38877473, 2024). "The tumor cells expressed SATB2, Bcl-2, TLE1, SMARCB1, but not CK, EMA, CD34, SMA, Desmin, S-100, CD99, STAT6, MyoD1, Myogenin, and Ki-67 LI is about 10%." (PMID 37361584, 2023). "Immunohistochemically (IHC), tumor cells were positive for SMA, MDM2, and p16; the cells were negative for desmin, MyoD1, Myogenin, pan-cytokeratin, S100, SOX10, HMB45, Malen-A, CD34, CD31, CD99, and ALK." (PMID 37735390, 2023).
tumor (continued). "Mitotic activity was low, and the tumor showed diffuse expression of α-SMA, desmin, caldesmon, and calponin, without expression of myogenin, MyoD1, CD34, EMA or PS100." (PMID 36421692, 2022). "Histopathology of the tumors and expression of tumor markers CD99, SPARC, and MyoD1 did not change significantly upon successive mouse‐to‐mouse passaging in 12 PDX models studied by IHC." (PMID 33837665, 2021). "Like the tumours in SCID/beige mice, these tumours also showed variable staining for VIMENTIN, DESMIN and SMA as well as an absence of staining for MYOD1 and MYOGENIN." (PMID 29731980, 2018). "The MYOD1 and NEFL genes were not expressed in either the nontumor or tumor regions; however, a high methylation level in the reads with SNV was detected only in the tumor areas." (PMID 41187747, 2025). "In this case, MyoD1 was negative and desmin and SMA were focally positive, which may represent a heterogeneous or incompletely differentiated state of the tumor cells." (PMID 40176092, 2025). "The tumor diffusely expressed NUTM1, was positive for WT1cter at weak to moderate intensity, and was focally positive for CD99, while it was negative for keratins, EMA, P40, MyoD1, myogenin, NKX2.2, BCOR, and pan-TRK." (PMID 38851744, 2024). "Mural nodules: polygon or spindle and giant tumor cells showed strong positive expression of cytokeratin (CK), epithelial membrane antigen (EMA), and vimentin (VIM), while CD163, S-100, Desmin, CD31, and MyoD1 were negative." (PMID 35836292, 2022). "The tumor cells show diffuse strong expression of Factor VIII, Fli-1, INI-1, vimentin, MDM2, and CDK4, local expression of CD31, AE1/AE3, EMA and P63, and no expression of CD34, S-100, actin-sm, desmin, MyoD1, and HMB45." (PMID 26315812, 2015). "Immunohistochemical examination indicates that the tumor cells were diffusely positive for Factor VIII, Fli-1, CDK4, INI-1, MDM2, vimentin, focally positive for AE1/AE3, CD31 and negative for actin-sm, CD34, desmin, myoD1 and S-100." (PMID 26315812, 2015).
cancer (47 papers, 1997 to 2026). A tumor composed of atypical neoplastic, often pleomorphic cells that invade other tissues. "We have selected five PCGIs (IGF2, SLC16A12, SOX11, P2RX7 and MYOD1) from cancer and inflammation/age related panels." (PMID 27259265, 2016). "Our previous work revealed that the cognate enhancer of MYOD1 is devoid of H3K4me1 and occluded by nucleosomes in cancer cells." (PMID 24916973, 2014). "However, MYOD1 is recently reported to function in upregulating various myogenic miRNAs transcription to inhibit cell proliferation or promote apoptosis, demonstrating an indirect role in cancer development." (PMID 33224130, 2020). "The methylation frequency of each gene ranks with only a few other genes methylated at high frequency in CRC (Cyclin A1, CDX1, RAR-β, MYOD1, p15INK4b and COX-2) in a cancer-specific manner." (PMID 19662090, 2009). "The analyzed genes in this work (SOX17, MYOD1, MAGI2, CDH1, AJAP1, MGMT, CDH13, and RASSF1A) participate in essential biological processes to maintain cell normality, and there is sufficient evidence for their protective role against the development of cancer." (PMID 34991696, 2022).